PTGS2 (prostaglandin-endoperoxide synthase 2)
Diseases named in the same sentence as PTGS2 in open-access papers (continued):
Sharing a sentence is not in itself a finding about the gene and the disease.
breast carcinoma (continued). "For example, activation of E2Fs following RB inactivation directly induces PTGS2, prostaglandin-endoperoxide synthase 2, in basal-like breast cancer cells." (PMID 32244804, 2020). "The results showed that the abnormal expression of 4 hub genes (PTGS2, ESR1, FOS, and NOS3) was associated with unfavorable overall survival of breast cancer patients." (PMID 33149754, 2020). "To explore the relationship between SIM2s and PTGS2 expression in breast cancer, we analyzed three different breast cancer cell lines including MCF7, DCIS.COM, and SUM159 cells." (PMID 31783895, 2019). "PACERR is the antisense gene of PGTS2 (prostaglandin-endoperoxide synthase 2) that has been related to colorectal cancer and breast cancer." (PMID 31242667, 2019). "Overexpression of PTGS2 has been detected in most types of cancer, including adenocarcinoma, hepatocellular carcinoma, colorectal cancer, breast cancer, pancreatic cancer, and lung cancers." (PMID 31920649, 2019). "Animal studies showed that overexpression of the PTGS2 in mammary glands can induce tumorigenesis, and that PTGS2 is often over-expressed in human breast cancer." (PMID 31690011, 2019). "One target gene of this pathway is PTGS2, which encodes for cyclooxygenase 2 (COX-2) and is upregulated in 40% of human breast carcinomas." (PMID 31783895, 2019). "Both of RGS4 and PTGS2 have been previously reported to involve in breast cancer cell proliferation and invasion." (PMID 26910917, 2016). "The overexpression of miR-26b inhibits cellular growth by targeting PTGS2, suggesting its use as a potential therapeutic target for breast cancer." (PMID 23374284, 2013). "Targeted knockdown of PTGS2 by siRNA significantly inhibited the proliferation of MDA-MB-231 breast cancer cells." (PMID 23374284, 2013). "The selection of PTGS2 as a critical gene for comparison is based on our previous result, which showed that PTGS2 is the top targeted gene by myrrh compounds, indicating an essential role played by PTGS2 in breast cancer tumorigenesis." (PMID 39707884, 2024). "Moreover, the GOBO analysis shows an elevated expression profile of the PTGS2/ESR2/EGFR/JUN/MMP2 genes’ signature in the most aggressive breast cancer subtype (Basal) in breast tumor samples and breast cancer cell lines." (PMID 39707884, 2024). "Notably, MMP9 had a staggering amplification frequency of 40.4% in colorectal cancer and 33.7% in esophagogastric cancer, while PTGS2 had an amplification rate of 34.1% in breast cancer." (PMID 37033970, 2023). "Taken together, these findings indicate that the expression of PTGS2, NFE2L2, and HMOX1 correlates with poor clinical outcomes and may be exploited as diagnostic and/or therapeutic targets in breast cancer." (PMID 33801351, 2021). "High expression of both PTGS2 and HMOX1was not statistically significant, but after about 8 years, it tended to be associated with the survival probabilities for breast cancer patients." (PMID 33801351, 2021). "However, coexpression of high levels of both PTGS2 and NFE2L2 was found to be significantly associated with the increased survival rate in breast cancer patients (p < 0.05)." (PMID 33801351, 2021). "Prostaglandin-endoperoxide synthase 2 (PTGS2) might mediate the CXCR2 signaling to inversely control the breast cancer metastasis and chemoresistance through the regulation of EMT, apoptosis, and senescence." (PMID 33708105, 2020). "Expression of PTGS2 has been suggested to promote breast cancer growth in vitro." (PMID 32577155, 2020). "The results showed that potential active ingredients of Poria cocos might interfere with breast cancer through synergistic regulation of PTGS2, ESR1, and FOS." (PMID 33149754, 2020). "Potential active ingredients of Poria cocos may interfere with breast cancer through synergistic regulation of key genes (PTGS2, ESR1, and FOS) that participate in the PPAR signaling pathway." (PMID 33149754, 2020).
breast carcinoma (continued). "PTGS2 gene expression experienced a 2.7-fold increase in breast cancer cells cultured under hypoxic conditions for 24 h when compared to normoxic conditions (p = 0.002), suggesting a role for this factor in the higher macrophage recruitment observed in H-N co-culture." (PMID 30788287, 2019). "In the 1833 xenograft model of skeleton metastasis from breast carcinoma the concomitant exposure to miR-125b mimic and NS-398, a specific PTGS2 chemical inhibitor, reduced and delayed the outgrowth of osteolytic bone metastases prolonging mice survival in respect to the single treatments." (PMID 29700305, 2018). "Our data showed overexpression of proinflammatory factors including CXCL1, CXCL2, CXCR4, CCL3, CCL4, IL-8, and PTGS2/COX-2 in the peripheral blood of patients with breast cancer both when considering the subtypes individually and when considering all breast cancer samples as a group." (PMID 26884644, 2016). "Analysis of the kmplotter database demonstrated that increased mean expression of ADAM17 and PTGS2 was associated with a non-significant trend towards reduced relapse free survival (RFS) in all breast cancer patients." (PMID 27738494, 2016). "This hypothesis was addressed by the experiments that increasing the expression of either GDF15 or PTGS2 mRNA in breast cancer cells generated same phenotype as IMP1 knockdown." (PMID 26910917, 2016). "Regarding the SNP rs5275 of PTGS2 in HCC1954, we found hints at a relation to breast cancer risk." (PMID 25710561, 2015). "At least seven genes (IL-11, CTGF, CXCR4, MMP-1, PTHrP, VEGF, and PTGS2/COX2) have been identified as drivers of human breast cancer bone metastases in the MDA-MB-231 model, and each of these genes is transcriptionally regulated by and dependent on TGFβ signaling in vivo." (PMID 24891760, 2014). "This suggests that PTGS2 promotes the proliferation of breast cancer cells in vitro." (PMID 23374284, 2013). "In conclusion, these findings support the hypothesis that decreased expression of PTGS2 by miR-26b accounts for the suppression of cellular proliferation in breast cancer." (PMID 23374284, 2013). "MiR-26b directly downregulates PTGS2 and inhibits breast cancer cell proliferation." (PMID 23374284, 2013). "The loss of TβRII in breast cancer cells can enhance recruitment of F4/80+ cells to tumor microenvironment and increase the expression of pro-inflammatory genes, including CXCL1, CXCL5 and PTGS2 (cyclooxygenase-2)." (PMID 22943793, 2012). "Our results indicate no strong association between the four most frequent PTGS2 SNPs and the risk of breast cancer." (PMID 21059239, 2010). "Moreover, some studies suggested that the addition of celecoxib to chemotherapy might adversely impact the prognosis of breast cancer patients, especially those with prostaglandin-endoperoxide synthase 2 (PTGS2) low tumors (NCT01041781)." (PMID 38520006, 2024). "Our findings highlighted several features of claudin-low breast cancer with potential therapeutic implications, including a low tumor mutational burden, high expression of the immune checkpoint gene CD274 (encoding PD-L1), and high expression of PTGS2 (encoding cyclooxygenase-2)." (PMID 31366361, 2019). "Expression of mRNA for COX2, P16/INK4A, and KI67 (encoded by PTGS2, CDKN2A, MKI67, respectively) and estrogen receptor beta (ERβ, encoded by ESR2) were analyzed because prior studies suggested these as biomarkers of AH at greater risk of progression to breast cancer." (PMID 31248446, 2019). "The present work indicates that variants in the PR and in the 3' UTR of PTGS2 do not appear to greatly influence breast cancer risk, as the apparent risk association found for rs5275 SNP was limited to heterozygotes with a low OR value and borderline significance." (PMID 21059239, 2010). "Similar results were obtained when examining the co-expression of PTGS2/ESR2/EGFR/JUN/and MMP2 genes’ signature in breast cancer cell lines representative of different molecular subtypes." (PMID 39707884, 2024).
breast carcinoma (continued). "For this purpose, we used the Gene expression-based Outcome for Breast Cancer Online (GOBO) dataset that contains data about 1881 breast cancer patients to produce a gene set composed of PTGS2/ESR2/EGFR/JUN/ MMP2 genes’ signature." (PMID 39707884, 2024). "To further dissect the biological contributions of the selected PTGS2/ESR2/EGFR/JUN/and MMP2 genes in breast cancer development, we studied their correlation, as a group, to different breast cancer molecular subtypes and ER / HR status." (PMID 39707884, 2024). "Among them, EGFR, MAPK1, MAPK3, PTGS2, and ESR1 were specifically evaluated for breast cancer treatment." (PMID 38794187, 2024). "The current analysis further certifies the decisive engrossment of PTGS2/ESR2/EGFR/JUN/MMP2 genes’ signature and some interactor proteins in promoting breast cancer development." (PMID 39707884, 2024). "These include PTGS2, EGFR, ESR2, MMP2, JUN, and HSP90AB1, which all revealed the highest mRNA expression level in the basal breast cancer subtype, thus proposing a potential similar engagement of these genes in the pathogenesis of the basal subtype." (PMID 39707884, 2024). "PTGS2 expression is induced by PGE2 and the inflammatory cytokine TNF-α, promoting the development of breast cancer in patients with CD." (PMID 37138170, 2023). "We constructed a novel 6-gene signature (SQSTM1, GDF9, LINC01125, PTGS2, GVINP1, and TMEM64) and used an XGBoost model to predict the metastatic status in breast cancer (AUC = 0.82)." (PMID 35436939, 2022). "PTGS2 and IL6 play important roles in the pathogenesis of breast cancer by promoting tumor growth, invasion, angiogenesis, and apoptosis resistance." (PMID 35682546, 2022). "Using the ORAI1 E106Q pore dead mutant and L273D STIM1 binding-deficient mutant, our study demonstrated that ORAI1 regulation of PTGS2 and IL6 expression in basal breast cancer is dependent on both ORAI1 pore activity and STIM1 binding." (PMID 35682546, 2022). "Targeted therapies have been developed for suppressing the post-partum pro-tumorigenic extracellular matrix via inhibition of PTGS2, and the potential benefit of targeting the FGF1 pathway in breast cancer has been considered." (PMID 36035177, 2022). "In breast cancer cells, overexpressing ci-miRNA-191, was associated with upregulated levels of TGF-β pathway genes (TGFβ2, SMAD3, BMP4, JUN, FOS, PTGS2, CTGF, and VEGFA), thus promoting breast cancer growth and metastasis." (PMID 32942528, 2020). "According to data analysed by Oncomine, mucinous breast carcinoma was the only breast tumour that had high expression of PTGS2, EGFR, and ABCB1, suggesting that expression of these genes vary based on breast cancer type." (PMID 32577155, 2020). "The results of network analysis show that RYNXC treat breast cancer by regulating the ESR1, PGR and PTGS2." (PMID 30906412, 2019). "In human breast cancer, downregulation of miR-26b can suppress cell apoptosis by targeting SLC7A11 and promote cellular growth by binding to PTGS2." (PMID 26204489, 2015). "CYP1A1, AHR, AR, CYP1A, CYP1B1 and PTGS2 genes are common in both PCB-gene and PCB-gene-breast cancer groups." (PMID 26512648, 2015).
breast carcinoma (continued). "In this study, we report that miR-26b expression is significantly decreased in human breast cancer, and its overexpression inhibits the proliferation of MDA-MB-231 cells by targeting PTGS2." (PMID 23374284, 2013). "Since overexpression of miR-26b suppressed the proliferation of MDA-MB-231 breast cancer cells, and given that PTGS2 is a direct target of miR-26b, we hypothesized that the inhibitory effect of miR-26b on breast cancer cell viability might be achieved via targeting PTGS2." (PMID 23374284, 2013). "PTGS2-induced PGE2 production promotes the migration and EMT of human breast cancer cells." (PMID 37138170, 2023). "PTGS2 and MMP9 had the highest amplification rates, with DCRGs amplified in bladder cancer, esophagogastric cancer, ovarian cancer, head and neck cancer, and breast cancer." (PMID 37033970, 2023). "Notably, three of these genes, including IGF1, PTGS2, and FGF1, were significantly related to breast cancer patient outcomes, thus further verifying their potential roles as prognostic biomarkers." (PMID 36035177, 2022). "In conclusion, our present research constructed a novel 6-gene signature (SQSTM1, GDF9, LINC01125, PTGS2, GVINP1, and TMEM64) by feature importance score and used an XGBoost model to predict the metastatic status in breast cancer (AUC = 0.82, higher than the previous studies to our knowledge)." (PMID 35436939, 2022). "This study identified ORAI1 as a regulator of PTGS2 and IL6 expressions in basal breast cancer." (PMID 35682546, 2022). "We speculated whether these 5 genes, LINC01125, GDF9, PTGS2, GVINP1, and TMEM64, contributed to breast cancer metastasis because of immune dysfunction and conducted an exploration from the immune cell perspective." (PMID 35436939, 2022). "The major transcriptional effects of DMHCA were linked to transrepression of a network of LXR-responsive genes, including PTGS2, S100A9, SPP1, CD14, CCL5 and ANXA1, which are overexpressed in MDSC and in a significant proportion of breast cancers, where they denote poor survival." (PMID 33780491, 2021). "Moreover, high expression of all three genes (PTGS2, NFE2L2, and HMOX1) correlated with poor prognosis in breast cancer patients." (PMID 33801351, 2021). "Further stratification of cancer types revealed pronounced subtype-specific anti-correlations of PTGS2 with CI genes, as shown for triple-negative breast cancer (TNBC) in both TCGA and Molecular Taxonomy of Breast Cancer International Consortium (METABRIC) datasets." (PMID 33220234, 2020). "The results indicated that ESR1, PGR, EGFR, PTGS2, and Src may be the potential therapeutic target of RYNXC for the treatment of breast cancer." (PMID 30906412, 2019). "The UALCAN analysis showed that only CXCL12 had a lower expression level in basal-like (triple-negative) breast cancer compared with luminal-like breast cancer, while CXCL5, IDO1, MIF, PTGS2, and VEGFA all had increased expression levels in basal-like breast cancer." (PMID 31293831, 2019). "In addition, we constructed an ingredients-targets-diseases network that show that RYNXC treated breast cancer by regulating the ESR1, PGR, and PTGS2." (PMID 30906412, 2019). "EBV oncogene LMP1 in NPC, PTGS2 in endometrial carcinoma and MYC in breast cancer may induce the BIRC5 expression by different pathways." (PMID 18570662, 2008). "Hence, targeting the ORAI1/STIM1 function in basal breast cancer cells could lead to a decrease in overall inflammatory signals through its effect on IL6 and PTGS2 expression." (PMID 35682546, 2022). "In addition, the mRNA expression of PTGS2 was significantly lower in breast cancer tissues than in normal tissues." (PMID 34335799, 2021).
breast carcinoma (continued). "Therefore, the downregulation of ESR1 and PTGS2 and upregulation of ESR2 by AESN might not only provide antitumor effects against ER+ breast cancer but also afford protective effects towards the development and progression of Parkinson’s disease and Alzheimer’s disease." (PMID 31835887, 2019). "Quick literature search revealed that PTGS2, EGFR, ABCB1, and IL6 high expression rather than low expression was correlated with breast cancer growth." (PMID 32577155, 2020).